ROR1 (ROR family WNT receptor 1)
Diseases named in the same sentence as ROR1 in open-access papers (continued):
Sharing a sentence is not in itself a finding about the gene and the disease.
chronic lymphocytic leukemia (continued). "The overexpression of ROR1 in malignancy was first identified on chronic lymphocytic leukemia (CLL) B cells and was subsequently found in many other hematological malignancies and solid tumors." (PMID 29850623, 2018). "We and others have demonstrated the overexpression of the ROR1 protein in chronic lymphocytic leukemia (CLL) and other lymphoid malignancies." (PMID 24205204, 2013). "Gene expression profiling identified ROR1, a receptor tyrosine kinase predominantly expressed in embryogenesis, as a signature gene in chronic lymphocytic leukemia (CLL), which we and others confirmed by a comprehensive analysis of ROR1 protein expression." (PMID 23285131, 2012). "The receptor tyrosine kinase like orphan receptor (ROR)-1 gene is overexpressed in chronic lymphocytic leukemia (CLL)." (PMID 20686606, 2010). "ROR1 prevalence varied significantly across distinct tumour types, showing 100% of ROR1 positivity in all chronic lymphocytic leukaemia (n = 48) and hairy cell leukaemia (n = 14) specimens analyzed via FC with ranges between 1.1–99.8% and 0.8–62.1%, respectively." (PMID 39495778, 2024). "ROR1 prefers expression over ROR2 in B-cell chronic lymphocytic leukemia (B-CLL) cells." (PMID 38601081, 2024). "Notably, cirmtuzumab, an anti-ROR1 mAb, reached phase I clinical trial in patients with relapsed chronic lymphocytic leukemia (LCC)." (PMID 38773263, 2024). "Furthermore, the designed immunosensor was applied for the analysis of ROR1 in several serum samples of chronic lymphocytic leukemia suffering patients with acceptable results, and it also exhibited good selectivity, reproducibility and stability." (PMID 34290319, 2021). "ROR1 expression in malignancies was initially noted in chronic lymphocytic leukemia (CLL)." (PMID 35844694, 2021). "Interestingly, a ROR1-targeting monoclonal antibody, cirmtuzumab, has been developed for the treatment of chronic lymphatic leukemia allowing future analysis of its effect on normal and ischemic heart." (PMID 30342492, 2018). "Strong expression of ROR1 was initially identified in B-Cell chronic lymphocytic leukemia (CLL)." (PMID 24752542, 2014). "ROR1, however, is overexpressed in B-cell chronic lymphocytic leukemia (CLL) cells." (PMID 20686606, 2010). "For instance, in hematological cancers the reactivation of ROR1 signaling in chronic lymphocytic leukemia (CLL), mantle cell lymphoma (MCL), and B-cell acute lymphoblastic leukemia (B-ALL) is linked to advanced disease stage and activation of AKT signaling in ROR1-high positive cells." (PMID 35504983, 2022). "We and others have previously demonstrated that RTK ROR1 is overexpressed in chronic lymphocytic leukemia (CLL)." (PMID 24205204, 2013). "Receptor tyrosine kinase-like orphan receptor 1 (ROR1), a member of the RTK family, is a tumor embryonic antigen expressed in various tumors, including chronic lymphocytic leukemia (CLL), ovarian cancer, and endometrial cancer." (PMID 38791529, 2024). "High expression of ROR1 is typical for some B-cell lymphomas such as mantle cell lymphoma (MCL) and chronic lymphocytic leukemia (CLL)." (PMID 35295854, 2022). "ROR1 is highly upregulated in chronic lymphocytic leukemia (CLL) B cells." (PMID 29850623, 2018). "Receptor tyrosine kinase-like orphan receptor 1 (ROR1) is selectively expressed on chronic lymphocytic leukemia (CLL) B cells and certain cancers, but is absent from normal B cells and healthy adult tissues." (PMID 41804382, 2026). "Phase I studies have shown the safety of targeting ROR1 in patients with chronic lymphocytic leukaemia, triple‐negative breast cancer and non–small cell lung cancer." (PMID 41355329, 2025). "ROR1 is highly expressed on the surface of chronic lymphocytic leukemia (CLL) cells but not on normal B-cells." (PMID 40869147, 2025).
chronic lymphocytic leukemia (continued). "Chronic lymphocytic leukemia (CLL) and mantle cell lymphoma (MCL) are malignancies characterized by the dependence on B-cell receptor (BCR) signaling and by the high expression of ROR1, the cell surface receptor for Wnt-5a." (PMID 35295854, 2022). "In chronic lymphocytic leukemia (CLL) cells a 64 kDa isoform with restricted nuclear expression as well as a 260 kDa isoform were identified, among which the latter probably represents a dimerized ROR1 (homo- or heterodimerized)." (PMID 33445713, 2021). "Also, chronic lymphocytic leukemia, hairy cell leukemia, and CML had significantly higher numbers of ROR1+ cells." (PMID 28637510, 2017). "Moreover, the neoplastic cells in chronic lymphocytic leukemia also appear dependent upon expression of ROR1, but do not express MET, suggesting that the function ROR1 also does not require HGFR in primary tumor cells." (PMID 22403610, 2012). "This indicates an exciting area for drug development, as minimal patient side effects may be seen, and, for the first time, a monoclonal ROR1 targeting antibody did not observe any off-target toxicity in preclinical studies and is now available in a phase I trial for Chronic Lymphocytic Leukemia." (PMID 26515598, 2015). "ROR1 is a receptor tyrosine kinase expressed in chronic lymphocytic leukemia (CLL) and several other malignancies but absent in most adult normal tissues." (PMID 26562161, 2015). "The under-expression of CD81, CD79b, and positive CD43 and ROR1 expression, noted in the DURAClone CLB panel specifically assists in distinguishing B-cell CLL from mantle cell lymphoma and other CD5 negative B-cell LPDs." (PMID 36483322, 2022).
ovarian carcinoma (56 papers, 2015 to 2026). A malignant neoplasm originating from the surface ovarian epithelium. "Clinical data show that an increase in ROR1 expression in ovarian cancers is associated with a higher rate of relapse and decreased overall and disease-free survival rates compared to cancers with low or no ROR1 expression." (PMID 40869147, 2025). "ROR1 overexpression has been associated with a poor prognosis in several solid and hematological malignancies, including ovarian cancer and other malignancies." (PMID 36672361, 2023). "The association between poor OS and ROR1 expression was high in endometrial cancer, followed by ovarian cancer, and diffuse large B cell lymphoma." (PMID 36557069, 2022). "In the case of receptor tyrosine kinase-like orphan receptor 1 (ROR1), higher expression of the gene was associated with a poor prognosis in ovarian cancer." (PMID 35887024, 2022). "In ovarian cancer, high ROR1 expression was likewise associated with tumor grade as well as lymph node metastasis." (PMID 33445713, 2021). "We identified the same association of ROR1 with higher grade in EC in ovarian cancer and pancreatic cancer." (PMID 32807831, 2020). "Receptor-tyrosine-kinase-like Orphan Receptor 1 (ROR1) is a tyrosine-protein kinase transmembrane receptor and ROR1 overexpression is associated with a poor prognosis in various cancers, including ovarian cancer." (PMID 29212222, 2017). "Ovarian cancers that express high levels of ROR1 had gene expression signatures associated with ovarian CSCs." (PMID 28491097, 2017). "Ovarian cancers that express high levels of Ror1 had gene-expression signatures associated with CSCs." (PMID 27571105, 2016). "Recent studies have reported a correlation between ROR1 expression and poor clinical outcome including relapse and survival in ovarian cancer patients and have even linked ROR1 to ovarian cancer stem cell migration and growth of tumour xenografts." (PMID 26515598, 2015). "Different to the oncogenic role of the two receptors in ovarian cancer where both receptors are overexpressed and associated with survival, our previous study in EC suggested distinct roles for ROR1 and ROR2, with high ROR1 and low ROR2 expression associated with shorter survival." (PMID 33494187, 2021). "Moreover, ROR1-positive ovarian CSCs have an enhanced ability to seed metastasis, form tumor spheroids, engraft immune-deficient mice, and migrate better, making ROR1 a prognostic marker for the shorter overall survival of ovarian cancer patients." (PMID 31382410, 2019). "However, the underlying mechanisms responsible for ROR1 action and promotion of ovarian cancer malignant phenotypes remain to be defined, which is also a limitation to our current study." (PMID 29212222, 2017). "Furthermore, the authors linked ROR1 with EMT, and showed that their anti-ROR1 monoclonal antibody inhibited ovarian cancer xenograft growth and reduced expression of EMT markers." (PMID 26515598, 2015). "In addition to stemness, ROR1 is also associated with chemoresistance in ovarian cancer." (PMID 40869147, 2025). "However, the potential of targeting ROR1 expressed by cancer-initiating cells such as those derived from ovarian cancer and glioblastoma may mitigate the risk of relapse and raise the potential of a cure." (PMID 28811962, 2017). "ROR1 can be found on the surface of exosomes and has been identified as a potential biomarker in human ovarian cancer, lung cancer, but also in PDAC." (PMID 38846943, 2024). "Molecular analyses have confirmed the high expression levels of ROR1 mRNA in human ovarian cancer biopsies compared to normal ovary samples and suggested ROR1 as a TAA and a promising therapeutic target for this type of neoplasm." (PMID 36873868, 2023). "Patients with ovarian cancer expressing high levels of ROR1 have a short median survival due to a small population of so-called cancer stem cells (CSCs)." (PMID 36873868, 2023).
ovarian carcinoma (continued). "In ovarian cancer, stroma cell expression of ROR1 was lower than in the tumor cells, while the opposite was true for ROR2." (PMID 33445713, 2021). "The expression of receptor tyrosine kinase-like orphan receptor 1 (ROR1) is closely related to the phenotype of ovarian cancer stem cells, peritoneal metastasis, and the development of resistance to chemotherapy." (PMID 34307378, 2021). "In ovarian cancer, a comparative analysis has revealed that ROR1 was largely expressed in cancer cells, while the number of patients with ROR2-positive tumors was significantly lower." (PMID 33445713, 2021). "In ovarian cancer ROR1 was described to have a synergistic effect with ROR2 on cell proliferation, since only a double knockdown led to a significant reduction in tumor cell proliferation." (PMID 33445713, 2021). "In ovarian cancer, tumor cells with high expression of ROR1 exhibited stem cell-like gene-expression signatures and had a greater capacity to engraft immunodeficient mice." (PMID 34123850, 2021). "This conclusion was based on observations in ovarian cancer stem cells, in which ROR1 was highly expressed and regulated the expression of the self-renewal marker polycomb complex protein BMI-1." (PMID 33445713, 2021). "Additional novel targets include the type 1 insulin-like growth factor receptor (IGF1R) and receptor tyrosine kinase-like orphan receptor 1 (ROR1) for sarcoma as well as the L1-cell adhesion molecule (L1-CAM) for ovarian cancer." (PMID 35008832, 2021). "The significance of ROR receptors in HGSC was supported further by studies that showed that ROR1 is overexpressed in ovarian cancer stem cells (CSCs) and can be effectively targeted for anti-cancer-stem-cell therapy." (PMID 31903136, 2020). "Here, we show that dexamethasone induces upregulation of ROR1 expression in ovarian cancer (OC), including platinum-resistant OC." (PMID 32989221, 2020). "In ovarian cancer, ROR1 is highly expressed on a subpopulation of tumor cells with features of CSC and ovarian cancers with high levels of ROR1 exhibit stem cell‐like gene expression signatures." (PMID 32281289, 2020). "Increased ROR1 expression resulted in elevated RhoA, YAP/TAZ, and BMI-1 levels in a panel of OC cell lines as well as primary ovarian cancer patient-derived cells, underlining the translational relevance of our studies." (PMID 32989221, 2020). "Ovarian cancers with high levels of ROR1 have stem cell-like gene expression signatures, as demonstrated by high levels of ALDH1 or the cell surface expression of CD133 and CD44." (PMID 31382410, 2019). "Treatment with a neutralizing antibody anti-ROR1 inhibits the capacity of ovarian cancer cells to form spheroids and to engraft immunodeficient mice and reduced the growth of tumor xenografts." (PMID 29389895, 2018). "Receptor tyrosine kinase-like orphan receptor 1 (ROR1) (a pseudokinase and receptor for Wnt5A) is expressed in ovarian cancer and is correlated with poor outcomes." (PMID 30042330, 2018). "Our previous study demonstrated that expression of ROR1 protein in ovarian cancer tissues was significantly higher than in normal ovary tissues and that ROR1 overexpression was associated with poor disease-free survival and overall survival." (PMID 29212222, 2017). "After obtaining and verifying the properties of ROR1-cFab, we assessed its antitumor activity in ovarian cancer cell lines." (PMID 29212222, 2017). "Our cell viability CCK8 data demonstrated that if the ROR1-cFab concentration was equal or greater than 40μg/mL, ROR1-cFab treatment was able to efficiently reduce the viability of ROR1-positive ovarian cancer cells in a time-dependent manner." (PMID 29212222, 2017). "Next, we assessed the pro-apoptotic effect of the ROR1-cFab on ovarian cancer cells using flow cytometric Annexin V-FITC/PI apoptosis assay." (PMID 29212222, 2017).
ovarian carcinoma (continued). "In murine models, ROR1 BiTE prevented the engraftment of pancreatic and ovarian cancer cells in xenograft models and reduced the size of established subcutaneous pancreatic tumors." (PMID 28811962, 2017). "Our resulting ROR1 BiTE facilitated efficient T-cell-mediated killing of pancreatic and ovarian cancer in vitro and in vivo as well as a range of solid tumor cell lines of different histological origins." (PMID 28811962, 2017). "Our wound healing and Transwell migration assays revealed significant inhibition of migration ability of ROR1-positive ovarian cancer cells at a dose of 40μg/mL ROR1-cFab for 24 or 48h." (PMID 29212222, 2017). "We then assessed antitumor effects of the generation antibody, ROR1-cFab, on ovarian cancer cell lines." (PMID 29212222, 2017). "Further studies are needed to determine if Wnt5a is responsible for the influence that ROR1 apparently has on the biology of ovarian cancer stem cells." (PMID 28491097, 2017). "Inhibition of ROR1 expression using miR382 suppressed ovarian cancer cell migration and invasion by downregulating epithelial-mesenchymal transition." (PMID 29212222, 2017). "This study developed a novel chimeric anti-ROR1 Fab antibody (named ROR1-cFab) and then assessed the antitumor activity of this antibody in ovarian cancer cells, an in vitro model of preclinical cancer therapy." (PMID 29212222, 2017). "We recently demonstrated that ROR2 and its sister receptor, ROR1, regulate ovarian cancer migration and invasion." (PMID 27239958, 2016). "In ovarian cancer cells, miR-382 inhibits cell migration and invasion by targeting ROR1 to regulate EMT20." (PMID 27830754, 2016). "In ovarian cancer, the Wnt5a receptor Ror1 was found to be highly expressed in high-grade and less-differentiated aggressive lesions and it was correlated with poor disease-free survival and overall survival." (PMID 27571105, 2016). "The use of primary cancer cells and investigations into ovarian cancer spheroids and tumourigenesis in vivo supports the role of ROR1 in ovarian cancer." (PMID 26515598, 2015). "In a cohort of 100 ovarian cancer patients, ROR1 was shown to be increased and statistically correlated with FIGO stage, tumour grade and lymph node metastasis." (PMID 26515598, 2015). "Recently, two papers have revealed that ROR1 is overexpressed in ovarian cancer and can be targeted for anti-cancer stem cell therapy in vivo." (PMID 26515598, 2015). "ROR1 has also been discovered on ovarian cancer stem cells yielding the potential to eliminate tumor initiating cells by targeting ROR1." (PMID 26030772, 2015). "Our study confirms the role of ROR1 in ovarian cancer progression, via our transwell migration and invasion assays." (PMID 26515598, 2015). "This trend is opposite to that reported of ROR1 in ovarian cancer, and ROR2 in other tumours, where ROR2 expression has been associated with worse overall or disease specific survival." (PMID 26515598, 2015). "A second recent paper confirmed the relationship of ROR1 to poor survival in the publically available database Gene Expression Omnibus, and also found that ovarian cancer cells with high ROR1 expression also featured stem cell like gene signatures." (PMID 26515598, 2015). "ROR2 expression is increased in epithelial ovarian cancer, and silencing ROR2 and its sister receptor ROR1 has a strong inhibitory effect on the ability of ovarian cancer cells to proliferate, migrate and invade through an extracellular matrix." (PMID 26515598, 2015). "Targeting ROR1 with zilovertamab-vedotin, a monoclonal antibody-drug conjugate, resulted in enhanced cytotoxicity, demonstrating a new approach against recurrent drug-resistant ovarian cancer." (PMID 41748546, 2026). "Additionally, high ROR1 expression in ovarian cancer cells showed stem cell-like gene-expression profiles." (PMID 37241228, 2023).